KIFBP (kinesin family binding protein)
Description:
Activator of KIF1B plus-end-directed microtubule motor activity. Required for organization of axonal microtubules, and axonal outgrowth and maintenance during peripheral and central nervous system development.
Synonyms: KBP; KIAA1279; KIF1BP; DKFZP586B0923; TTC20
Tractability: Small molecule: a structure with a bound ligand is known. PROTAC: ubiquitination databases record sites on it.
Gene: Protein-coding gene on chromosome 10 (68,988,803 to 69,043,544, forward strand). Ensembl gene ENSG00000198954.
Subcellular location: Cytoplasm, cytoskeleton
Gene Ontology:
Molecular function: kinesin binding; protein binding; protein sequestering activity
Biological process: mitochondrion transport along microtubule; transport along microtubule; central nervous system projection neuron axonogenesis; microtubule cytoskeleton organization; neuron projection maintenance
Cellular component: cytoskeleton
Genetic constraint (gnomAD): Loss-of-function variants: 34 observed, 44.57 expected, observed/expected ratio (o/e) 0.76, 90% interval 0.58 to 1.02. The synonymous counts are far from expectation, so gnomAD's model fits this gene poorly and the ratio says little. Missense variants: 583 observed, 710.7 expected, observed/expected ratio (o/e) 0.82, 90% interval 0.77 to 0.88. Synonymous variants: 224 observed, 278.28 expected, observed/expected ratio (o/e) 0.8, 90% interval 0.72 to 0.9.
Gene-disease validity (ClinGen):
ClinGen rates the evidence that KIFBP causes each of these diseases.
Goldberg-Shprintzen syndrome (autosomal recessive): Definitive.
Homologues: Orthologues: chimpanzee KIFBP (99% identical), dog KIFBP (95% identical), rabbit KIFBP (95% identical), pig KIFBP (94% identical), mouse Kifbp (92% identical), guinea pig KIFBP (91% identical), rat Kifbp (90% identical), tropical clawed frog kifbp (60% identical), zebrafish kifbp (55% identical), Drosophila melanogaster CG14043 (29% identical).
Diseases named in the same sentence as KIFBP in open-access papers:
KIFBP is named in the same sentence as 21 diseases in open-access papers, as found by Europe PMC text mining. Sharing a sentence is not in itself a finding about the gene and the disease. The quoted sentences say what the papers report.
Goldberg-Shprintzen syndrome (15 papers, 2010 to 2024). A multiple malformation syndrome characterized by Hirschprung megacolon with microcephaly, hypertelorism, submucous cleft palate, short stature and learning disability. "Homozygosity mapping followed by sequence analysis in a consanguineous family with multiple members having Goldberg–Shprintzen syndrome (GOSHS) identified homozygous truncating mutations in KIAA1279 (KIFBP)." (PMID 34422713, 2021). "Goldberg–Shprintzen syndrome (GOSHS) is caused by loss of function variants in the kinesin binding protein gene (KIFBP)." (PMID 32939943, 2020). "Kinesin-binding protein (KIFBP), which is mutated in Goldberg-Shprintzen syndrome, binds to and inhibits the catalytic motor heads of 8 of 45 kinesin superfamily members, but the mechanism remains poorly defined." (PMID 34797717, 2021).
KIFBP also shares sentences with these, for which no sentence is quoted: Intellectual disability (5 papers); neuroblastoma (4); axonal neuropathy (3); Hirschsprung disease (3); microcephaly (2); neurological disorder (2); tumor (2); cancer (1); developmental delays (1); gastric cancer (1); Gastrointestinal obstruction (1); Hypertension (1); Insulin resistance (1); megacolon (1); neurodegenerative disease (1); Obesity (1); peripheral neuropathy (1); polymicrogyria (1); respiratory failure (1); schizophrenia (1).